TNF (tumor necrosis factor)
Diseases named in the same sentence as TNF in open-access papers (continued):
Sharing a sentence is not in itself a finding about the gene and the disease.
infection (continued). "Consequently, these observations indicate that TNF-α and IL-10 protect significant proportions of mice from fatal infection by pathogenic JaOArS982 virus." (PMID 23940775, 2013). "Furthermore, TNF-α therapy is implicated in the increased risk of serious infections and malignancies." (PMID 24283517, 2013). "TNF-α is required to control the infection caused by B. pseudomallei in mouse models." (PMID 23508691, 2013). "TNF deficient mice rapidly lost weight and succumbed by 6 weeks of infection with highly inflammed lung, spleen and liver, while IL-1R1 and IL-1α plus IL-1β deficient mice survived systemic M. bovis BCG infection with lung, spleen and liver weight similar to wild-type mice at 6 and 11 weeks." (PMID 25400917, 2013). "However, upon infection, Fas- and FasL-deficient mice showed significantly less TNF-α production in the vaginal lavages at 3 day of infection in comparison to wild-type C57BL6 mice (p≤0.05)." (PMID 23922974, 2013). "Although TLR2-deficient mice exhibited hepatic levels of TNF-α equivalent to those in WT mice at 6 h post-infection, a subsequent decrease in hepatic TNF-α levels was significantly delayed in TLR2-deficient mice with 7.7-fold higher levels at 3 d post-infection (vs. WT mice)." (PMID 24058538, 2013). "However, iNOS-deficient cells expressed high levels of TNF-α, which is potentially associated with an efficient activation of dendritic cells and increased migration of inflammatory cells to the site of infection." (PMID 23936574, 2013). "Accordingly, we show here that mycobacteriophage D29 treatment was associated with increased levels of both IFN-γ and TNF in M. ulcerans-infected footpads, correlating with a predominance of a mononuclear infiltrate and prevention of ulceration at 150 days post-infection." (PMID 23638204, 2013). "Notably, TNFα deficient mice appear to have innately larger LN feed arteriole prior to infection than we have previously noted in wild-type C57 BL/6 background controls." (PMID 23573281, 2013). "Another study, also in Brazilian patients, suggested that allele TNF-238A, which correlates with production of significantly higher levels of TNF-α, could influence the susceptibility to infection." (PMID 24069594, 2013). "Early in infection, the protective effects of iNOS deficiency was associated with decreased fungal burdens, enhanced secretion of TNF-α augmented DTH reactions, and increased migration of activated T cells and macrophages to the lungs, which subsequently organize as well-compact granulomas." (PMID 23936574, 2013). "TNF-α plays an important role in host defense and anti-TNF-α agents may theoretically increase the risk of infections." (PMID 22645622, 2012). "Experiments with recombinant BCG-expressing TNF-α demonstrated that high levels of TNF-α could cause destructive inflammation; the relative amount of TNF-α at the site of infection determined whether the cytokine acts as a protective or a destructive mediator." (PMID 23213508, 2012). "The capsule of serotype 2, the most common serotype associated with infection in humans and pigs, was highly anti-phagocytic and modulated the IL-10/IL-12 and IL-10/TNF-α cytokine production in favor of a more anti-inflammatory profile compared to other serotypes." (PMID 22558240, 2012). "Infection in susceptible hosts are modulated by type 2 immune response with Th2 cells that produce IL-4 and IL-13 while protection is associated with type 1 immune response largely dependent of TNF-α and IFN-γ." (PMID 22851964, 2012). "This is reflected in the recent labelling update issued by the Food and Drug Administration, in which the warnings and precautions for TNF-α inhibitors have been revised to ensure consistency of information on the risk of serious infections and the associated pathogens." (PMID 22925480, 2012).
infection (continued). "So far, the significance of specific candidate genes in SPTB has been assessed in numerous case-control studies, focusing mostly on genes involved in the infection and inflammation pathway, such as those encoding tumor necrosis factor α (TNF-α) and several interleukins." (PMID 23227263, 2012). "The role of TNF-α may depend upon the presence of INF-γ early in the infection, since when TNF-α is neutralized in INF-γ deficient mice there is an increase of macrophages, NK cells and neutrophils in the spleens." (PMID 22500859, 2012). "Importantly, inactivation of TNFα interferes with innate immune defense and predisposes a risk of pathogenic infection." (PMID 22479635, 2012). "In primary infection, decreased survival of TNF-α-deficient mice has been attributed to an impaired ability to generate reactive nitrogen intermediates in the alveolar macrophages, although inducible nitric oxide synthase expression in lung tissue is preserved." (PMID 22007223, 2012). "The reduced effector and memory B cell response we observed in anti-TNF-treated patients, may contribute to the increased risk and severity of infection observed in anti-TNF-treated patients." (PMID 22177419, 2011). "During severe infection, uncontrolled release of cytokines such as tumor necrosis factor-alpha (TNF-α) and interleukin-6 (IL-6) may cause a so-called cytokine storm." (PMID 21931850, 2011). "As TNF plays an important role in the host defense mechanism against intracellular pathogens, anti-TNF therapy is associated with increased risk of infection with intracellular micro-organisms, such as Mycobacterium tuberculosis, Listeria monocytogenes and Legionella pneumophila." (PMID 22081766, 2011). "Recommendations have been published to reduce the infection risk with the use of TNF-α blockers." (PMID 22567476, 2011). "The cytokine profile in reactivating Tm-TNF mice reported here contrasts to that observed in de novo infected Tm-TNF mice with respect to pulmonary IFNγ AND IL-10 concentrations during late stage infection despite similar observed susceptible phenotypes." (PMID 22132068, 2011). "However, there was a significant decrease in IL-12p70 and IFNγ pulmonary concentrations in Tm-TNF compared to WT mice 322 days post-infection associated with susceptibility of Tm-TNF mice to M. tuberculosis reactivation at this time point." (PMID 22132068, 2011). "The limited data available on abatacept suggest that the risk of serious infections with these products may be more limited than that of the TNF inhibitors." (PMID 22081766, 2011). "A number of case reports indicate that treatment with TNF inhibitors may lead to an increased susceptibility for infection with different salmonella species." (PMID 22081766, 2011). "A recent study using data from the North American CORRONA registry indicates that MTX and TNF inhibitor therapy and the combination of both are all associated with a comparable increase in the incidence of overall infections as well as opportunistic infections." (PMID 22081766, 2011). "IFN-γ, TNF, and NF-κB were linked to the largest number of differentially expressed genes, indicating their important roles in the regulation of gene expression responses due to ST infection." (PMID 22174891, 2011). "Taken together, our data suggests that an increase in TNFα level may cause down regulation of SOD1 in HSAECs and that MP12 infection causes a modest up regulation of TNFα gene transcription." (PMID 21655261, 2011). "The present study suggests that a previous TJA infection before the introduction of TNFα blockers could be a risk factor of reoccurence, although statistical significance was not reached." (PMID 20637100, 2010). "Some studies have demonstrated that the use of corticosteroids may increase infection risk as well as anti-TNF agents given to patients with RA." (PMID 20398273, 2010).
infection (continued). "Following infection of epithelial cells by S. flexneri, the activation of NF-κB leads to the upregulation of genes encoding for inflammatory cytokines including IL-8 and TNFα." (PMID 20976174, 2010). "If TNF-α and IL-1β were critical host-components leading to the attenuation observed in mice infected with CO92ΔyopH, then it would not be unreasonable to predict that mice deficient in these molecules would be more sensitive to infection with CO92ΔyopH." (PMID 20565713, 2010). "Anti-TNF agents have a substantial risk of infection with Mycobacterium tuberculosis." (PMID 21083879, 2010). "Given the serious illnesses and deaths caused by these infections, whether anti–TNF-α therapy can be safely continued during antimycobacterial therapy is not clear." (PMID 19861045, 2009). "Recently, a population of DC expressing CD11b+ CD11c+ LY-6C+ MHC-II+ and high levels of iNOS protein (termed inflammatory DC or TNF-iNOS-producing DC (Tip-DC)) has been implicated in the resistance to infection by intracellular bacteria (e.g. Listeria monocytogenes and Brucella melitensis)." (PMID 19557162, 2009). "However, the severity of the lesions in the footpads four weeks post-infection (p.i.)highlighted a more crucial role for iNOS compared to TNF-α in this pathogenic model." (PMID 19557162, 2009). "Pro-inflammatory in vitro recall responses (i.e. IFN-γ, IL-12p70, TNF-α and the ratio of TNF-α to bioactive TGF-β) were associated with the ability to control parasite growth (length of time to first detection of 1000 parasites/mL) after challenge infection." (PMID 19691558, 2009). "Cancer patients undergoing treatment with systemic cancer chemotherapy drugs often experience debilitating fatigue similar to sickness behavior, a normal response to infection or tissue damage caused by the production of the inflammatory cytokines IL-1β, TNF-α, and IL-6." (PMID 18523641, 2008). "Therefore, the anti-TNFα cohort in a “receiving treatment” analysis had a progressively lower risk of infection over time because of the selective exclusion of high-risk patients." (PMID 17763441, 2007). "For patients who have a serious infection while receiving anti-TNFα therapy, clinicians will decide whether treatment should be resumed, based on their opinion of further infection risk." (PMID 17763441, 2007). "Surprisingly, there have been only a few isolated case reports in the literature accessing the efficacy of anti-TNF treatment, perhaps due to the failure of corticosteroids as well as to the increased risk of infections associated with current anti-TNF biologics." (PMID 17205112, 2006). "Regarding safety, integrin inhibitors generally present a lower risk of infections and malignancies compared to anti-TNF therapy, However, case reports have indicated that vedolizumab may be associated with rare pulmonary inflammation (eosinophilic pneumonia) or virus-associated malignancies." (PMID 41495287, 2026). "TNF-α inhibitors may be necessary in more advanced cases; however, they carry an infection risk." (PMID 40225494, 2025). "Likewise, there is insufficient data to direct patient selection for TNF-α inhibitors, as they may be beneficial but also have significant infection risk." (PMID 40225494, 2025). "The analysis revealed a significant upregulation of tumor necrosis factor-alpha (TNF-α) and interleukin-1 beta (IL-1β) in the PbA-infected untreated group, compared to the uninfected control group (p < 0.05), indicating a heightened inflammatory response associated with infection." (PMID 40892845, 2025). "Additionally, SNPs in genes encoding IL-10 and TNF-α, two major cytokines involved in the neonatal inflammatory response, underscore the potential for inherited variation in immune signaling to shape infection outcomes." (PMID 40927580, 2025).
infection (continued). "We showed a significant induction of immune response (significant upregulation of TNF-α and IL-6) by PHGFs infected with each P. gingivalis strain harbouring the G231N, E232T, N235D variant in comparison with expression of both genes due to infection with wt-P." (PMID 40004125, 2025). "Additionally, the immunosuppressive treatments commonly used in RA management, including intra-articular corticosteroids, disease-modifying antirheumatic drugs (DMARDs), and biologics such as anti-TNF agents, further suppress immune function, predisposing patients to infections." (PMID 40606458, 2025). "Based on current evidence, the IL-23 p19 inhibitors could be considered in a stratified treatment model, which could serve as the first-line options for biologic-naïve patients with high infection risk or comorbidities, alongside the second-line agents for those with anti-TNF failure." (PMID 40356994, 2025). "Infections with VacA/CagA-positive strains are associated with intense neutrophil infiltration and a strong inflammatory response mediated by ROS and interleukins (IL-1 α, IL-1 β, IL-2, IL-8, and TNF α), extensive DNA damage in epithelial cells, and morphological alterations." (PMID 39942791, 2025). "Due to the immunosuppressive effects of TNF-α inhibitors, individuals who use these medications face a higher risk of infections and may experience a more severe progression of their condition compared to healthy individuals who are not on immunosuppressive treatments." (PMID 40763141, 2025). "This causes the release of IL-6, IFNβ, and TNF; the latter activates pro-inflammatory pathways of NF-κB, and in this way, a vicious cycle and cytokine storm arise, recruiting immune cells (mainly T-cells in the case BoDV1 infection, although BoDV1 suppress RIG activation) to the site of infection." (PMID 38339126, 2024). "Compared to Prévotella bivia infection of three-dimensional human vaginal epithelial cells or GV infection of cervical epithelial cells, AV can induce a more intense pro-inflammatory immune response, causing vaginal epithelial cells to secrete a large amount of IL-6 and TNF-α." (PMID 39027438, 2024). "Consequently, anti-TNF-treated patients with IBD face an increased risk of breakthrough infection." (PMID 39066413, 2024). "This infection leads to chronic inflammation, which may accelerate carcinogenesis through the secretion of proinflammatory cytokines such as TNF-alpha, IL-1β, and IL-6, which in turn increase the risk of DNA damage and mutations, which promotes the transformation of cancer cells." (PMID 39451226, 2024). "Our research shows that infection of rabbits with L. europaeus/GI.1 and GI.2 genotypes causes an increase in the expression of two critical acute phase cytokines—IL-6 in all examined tissues (liver, lungs, kidneys, and spleen) and TNF-α (in the liver, lungs, and spleen)." (PMID 39273479, 2024). "Hence, the increase in TNF-α expression might be implicated in the decreasing phenotypic effect of LV-infection in DLD-1 cells." (PMID 39427065, 2024). "In VL, Th1 cells produce pro-inflammatory cytokines such as IFN-γ and TNF-α, which induce phagocytic activity and control parasitic growth while Th2 cells produce a higher level of IL-4, IL-5, IL-13, and IL-10 that leads to susceptibility towards infection (Refs." (PMID 39587036, 2024). "The data in BALB/c mice are consistent with our previous studies in CBA/J mice demonstrating that following infection with C. neoformans, cda1∆2∆3∆-vaccinated mice had increases in pulmonary cytokines and chemokines often associated with Th1-type responses, including IFNγ and TNFα." (PMID 38980038, 2024). "Thus, the continuity of platelet activation and DKK1 production observed at later phase of infection may be associated with TNF-alpha activated platelets." (PMID 37885890, 2023). "Therefore, fewer studies have reported on infections caused by non-TNF α inhibitors." (PMID 38013343, 2023).
infection (continued). "Establishing the IL-10:TNF-α ratio as a reliable biomarker for burn injury severity and predictor of susceptibility to repeat infections could be clinically valuable for identifying high-risk patient groups and implementing more personalized risk-stratified management of patients." (PMID 37180165, 2023). "A later elevation in TNF-α expression may be indicative of the onset of infection caused by MPs." (PMID 37998029, 2023). "Patients who delayed going to the hospital > 48 h past the onset of symptoms had higher serum TNF levels, lower blood pressure (< 90 mmHg), and lower oxygen saturation levels at the time of admission; all of which are associated with poorer outcomes during infection." (PMID 36870980, 2023). "Additionally, the analysis of SAPS-related inflammatory cytokines and chemokines in the supernatant of the infected lung slices revealed that infection with the omicron variant exclusively triggered an increased secretion of IL-1b, IL-6, IL-8, TNF-α, and IL-1β." (PMID 38095608, 2023). "Moreover, these soluble biomarkers, in conjunction with LPS-induced TNFα, could be used as a standard method to identify those at risk for infection after burn injury." (PMID 35958579, 2022). "The down-regulatory effect of urolithin M5 on NF-κB, TNF-α and IL-6 was beneficial for the influenza virus-infected mice since excessive pro-inflammatory cytokines/chemokines may cause severe tissue damage after infection." (PMID 36080488, 2022). "Indeed, infection of IL-10-/- mice with P. chabaudi chabaudi led to exacerbated pathology which was linked to increased expression of pro-inflammatory cytokines such as IFNγ, IL-12 and TNF." (PMID 35464430, 2022). "In addition, pathogenic infections can activate or control TNF-α/NF-κB-mediated signaling pathways." (PMID 36139883, 2022). "Therefore, treatment with TNF inhibitors could impair immunity and thereby increase the potential risk of infection and cancer." (PMID 35945635, 2022). "In summary, the ABO blood group might be an essential factor influencing the time of viral clearance and the intensity of the TNF-α-associated response over time post-infection and further studies with additional evaluated individuals could confirm such results." (PMID 34967260, 2022). "Due to their immunosuppressive functions, individuals taking TNF inhibitors are at a heightened risk of infection and at risk for a more severe course compared to healthy individuals not taking immunosuppressants, with up to 14% of individuals discontinuing TNF inhibitor treatment due to infections." (PMID 36159650, 2022). "Therefore, Glycyrol may also regulate TNF to reduce cell damage and death thereby alleviating damage from the inflammatory response caused by infection." (PMID 36506032, 2022). "In this study, concentrations of IL-1β and TNF-α in bMECs culture medium increased significantly after bMECs were infected with K. pneumoniae; furthermore, there was a positive association with duration of infection time, confirming K. pneumoniae-induced inflammation of bMECs." (PMID 33468111, 2021). "The early infection (3 dpc) triggered a strong transcriptional up-regulation of many immune genes in different organs including those encoding pro-inflammatory cytokines IL-1β, IL-6 and TNFα and other cytokines involved in the development of adaptive immunity (IL-8, IL-10, IL-22, IL-17C2, INFγ)." (PMID 34497310, 2021). "The concomitant useof TNF-α antagonists may increase the risk of infection and shouldbe avoided." (PMID 34430870, 2021).